NRAS (NRAS proto-oncogene, GTPase)
Diseases named in the same sentence as NRAS in open-access papers (continued):
Sharing a sentence is not in itself a finding about the gene and the disease.
thymoma (13 papers, 2012 to 2025). A neoplasm arising from the epithelial cells of the thymus. "In these studies, GTF2I mutation was accompanied with HRAS and NRAS mutations, suggesting a potential exclusivity to indolent thymomas." (PMID 38338833, 2024). "One thymic carcinoma harbored a NRAS and three type A thymomas a HRAS mutation." (PMID 27844328, 2017). "Additionally, the authors documented AKT3, ALK, CSF1R, FGFR4, KRAS, NRAS, and PIK3CA as common mutated genes in thymomas." (PMID 38338833, 2024). "In The Cancer Genome Atlas study of 117 early-stage, resected thymic tumor specimens, molecular hallmarks of thymomas, which accounted for the majority of cases of this study, also included GTF2I mutations, specific for type A, and mutations in HRAS and NRAS mutations." (PMID 35749302, 2022). "Significant enrichment of mutated genes of the RAS and PI3K-Akt signalling pathways was reported in thymomas (AKT3, ALK, CSF1R, FGFR4, KRAS, NRAS, HRAS, PIK3CA), and their role in thymoma development was suggested." (PMID 35884448, 2022).
chronic myelomonocytic leukemia (12 papers, 2013 to 2025). A myelodysplastic/myeloproliferative neoplasm which is characterized by persistent monocytosis, absence of a Philadelphia chromosome and BCR/ABL fusion gene, fewer than 20 percent blasts in the bone marrow and blood, myelodysplasia, and absence of PDGFRA or PDGFRB rearrangement. "We compared features in NRAS-mutated patients of the Austrian biodatabase for chronic myelomonocytic leukemia (ABCMML) with the chronic myelomonocytic leukemia (CMML) cohort documented in cBioPortal." (PMID 40372530, 2025). "In 2 patients (patient 19 with ECD/chronic myelomonocytic leukemia and patient 37 with B-ALL/HS), identical NRAS/KRAS mutations were identified in both neoplasms, suggesting a clonal relationship." (PMID 40453055, 2024). "Monocytosis, defined by increased monocyte levels, is significant in Chronic Myeloid Leukemia and Chronic Myelomonocytic Leukemia (CML and CMML), with mutations in ASXL1 and NRAS contributing to disease progression." (PMID 41141324, 2025).
juvenile myelomonocytic leukemia (12 papers, 2015 to 2025). A myelodysplastic/myeloproliferative neoplasm of childhood that is characterized by proliferation principally of the granulocytic and monocytic lineages. "NRAS mutations are well-known drivers of oncogenesis and have been associated with hematologic malignancies, including juvenile myelomonocytic leukemia (JMML) and ALPS." (PMID 40616106, 2025). "Juvenile myelomonocytic leukemia (JMML) is a rare pediatric MDS/MPN overlap syndrome that is characterized by somatic mutations in NF1, CBL, NRAS, KRAS or PTPN11 that result in the activation of RAS/MAPK or JAK/STAT signaling." (PMID 31171568, 2019).
nodular melanoma (12 papers, 2016 to 2025). "Mutations in NRAS were correlated to nodular melanoma (odds ratio = 1.57), localized in the limbs (odds ratio = 1.31)." (PMID 31274706, 2020). "In contrast, NRAS mutations were more commonly found in nodular melanomas (19.4%) compared to either BRAF mutant (8.6%) or WT tumors (15.3%)." (PMID 27191502, 2016). "We also observed that 24.1% of NRAS-mutant tumors proved to be nodular melanoma, while 16.7% of BRAF-mutant and 17.9% of double-wild-type tumors belonged to that histological category." (PMID 34209415, 2021).
acute lymphoblastic leukemia (11 papers, 2011 to 2025). Leukemia with an acute onset, characterized by the presence of lymphoblasts in the bone marrow and the peripheral blood. "SPI1 fusion genes in T-cell acute lymphoblastic leukemia (T-ALL) are commonly found with co-occurring NRAS mutations." (PMID 34230493, 2021). "NRAS mutations are known to be prevalent in certain hematologic malignancies, including AML and acute lymphoblastic leukemia." (PMID 38363781, 2024). "NRAS or KRAS mutations detected in approximately 20–40% of myeloid malignancies and 10–15% of acute lymphoblastic leukemia cases." (PMID 39048945, 2024). "Mutations in FLT3, KRAS, NRAS, and BRAF genes have been observed with variable prevalence (5-20%) in acute myeloid (AML) and lymphoblastic leukaemias (ALL)." (PMID 24571676, 2014). "Mutations in RAS pathway proteins (e.g., KRAS, NRAS, FLT3, PTPN11, and NF1) are highly prevalent in acute lymphoblastic leukemia (ALL), with such mutations occurring in 40%–50% of pediatric B cell ALL cases." (PMID 35243242, 2022). "Kinase profiling revealed that GNF-7 not only evidently inhibited LYN, FYN, SRC, YES, BTK and CSK kinase that can also inhibited by dasatinib, but also inhibited ACK1 and mitogen-activated protein kinase (GCK) to kill NRAS-dependent cells in AML and acute lymphoblastic leukemia." (PMID 38037057, 2023).
myeloid leukemia (11 papers, 2015 to 2024). A clonal proliferation of myeloid cells and their precursors in the bone marrow, peripheral blood, and spleen. "In agreement, while Rab27b–/– mice display no obvious abnormalities, Rab27b deficiency significantly abrogated myeloid leukemia development conferred by oncogenic NRAS." (PMID 37317963, 2023). "NRAS mutations are frequent in human myeloid leukemias and other cancers and the G12D mutation has been described to drive development of chronic MPN in mice." (PMID 32660441, 2020). "In human cancers with NRAS mutations, G12 mutations are notably prevalent in myeloid leukemia." (PMID 38612443, 2024). "One of the patients with NRAS and JAK2 mutations had myeloid leukemia with a prior described JAK2 mutation." (PMID 39000050, 2024). "It has been reported that EZH2 inactivation and oncogenic NRAS mutations together activate BCAT1, enhance BCAA metabolism and mTOR signaling, and promote the development of myeloid leukemia." (PMID 39324007, 2024). "Rab27b deficiency in mice inhibits oncogenic NRAS-mediated signaling, HSPC growth, and myeloid leukemia development in vivo." (PMID 37317963, 2023). "Taken together, these data demonstrate that Rab27b deficiency abrogates oncogenic NRAS-mediated ERK signaling and myeloid leukemia development in vivo." (PMID 37317963, 2023). "We have previously shown that both oncogenic NRAS and KRAS4B can induce myeloid leukemia in a mouse bone marrow transduction/transplantation (BMTT) model." (PMID 26715448, 2015).
seminoma (11 papers, 2018 to 2025). A radiosensitive malignant germ cell tumor found in the testis (especially undescended), and extragonadal sites (anterior mediastinum and pineal gland). "A recent analysis of the Cancer Genome Atlas demonstrated that KIT, KRAS, and NRAS gene variants were observed only in seminoma, while gene variants in B3GNT8, CAPN7, FAT4, GRK1, TACC2, and TRAM1L1 occurred only in embryonal carcinoma." (PMID 41426877, 2025). "We demonstrate clear association in seminomas of CN-Sig-1 with KRAS/NRAS/KIT-mutation, a phenomenon also observed in HGSOC27." (PMID 32366847, 2020). "Several genomewide studies suggested driver mutations in only three genes (KIT, KRAS, and NRAS) in 4–31% of seminoma, and up to 14% of non-seminoma patients." (PMID 30547014, 2018). "RAS mutations clustered at known mutation hotspots and mutations in KRAS and NRAS co-existed in only one seminoma." (PMID 29898407, 2018). "In addition, KRAS mutations were found in two EC, four seminoma, two MMGCT, and two YST, and NRAS mutations in one seminoma and one YST." (PMID 37149691, 2023). "KIT, KARS and NRAS observed at very high mutation frequency were mainly occurred in seminoma." (PMID 36713456, 2022). "Differences in somatic mutations between subtypes are also of concern, with our results suggesting that mutations in some genes (B3GNT8, CAPN7, FAT4, GRK1, TACC2, and TRAM1L1) occur only in embryonal carcinoma, while mutations in KIT, KARS, and NRAS are observed only in seminoma." (PMID 36713456, 2022). "These tumours show a low rate of mutations compared to common cancers, which would make the prediction of mutations by AI more challenging, although somatic mutations of the KIT gene and its downstream mediators encoded by the KRAS and NRAS genes have shown significance in seminoma." (PMID 33809521, 2021). "Association with seminoma was found for mutations in KIT, KRAS and NRAS and for putative oncogenic driver genes CBL, RAC1, PIK3CA, and CTNNB1 (analysed jointly due to lower frequency), p = 3.33 × 10−10, p = 1.41 × 10−6, p = 0.002, p = 0.009, respectively." (PMID 32366847, 2020). "The number of expressed CT genes was significantly higher in seminomas (P = 3.48 × 10−13) which were characterized by frequent mutations in driver genes (KIT, KRAS and NRAS)." (PMID 31070303, 2019). "Of the six seminomas with mutations in both KIT and KRAS/NRAS, four were in men with a history of cryptorchidism (odds ratio = 7.3 [95% confidence interval 1.2–45.0]), all in the ipsilateral testicle." (PMID 29898407, 2018). "Somatic mutation of only three genes achieved significance—KIT, KRAS, and NRAS—exclusively in samples with seminoma components." (PMID 29898407, 2018). "Additionally, they found a small but significant association between NRAS mutations and seminomas, a finding not replicated in our cohort." (PMID 41009531, 2025). "While WGD was typically among the earliest events in TGCTs, a subset of seminomas (N=25, 17.4%) harbored driver mutations in KIT, KRAS, NRAS, or PIK3CA prior to WGD, irrespective of WGD timing." (PMID 40568177, 2025). "Several genome wide studies has been conducted in GCTs: in 4–31% of seminomas, and up to 14% of non-seminomas, driver mutations were detected in three genes (KRAS, NRAS and KIT)." (PMID 36860862, 2023). "As described in our results, mutation that only occurs in embryonal carcinoma (B3GNT8, CAPN7, FAT4, GRK1, TACC2 and TRAM1L1) or seminoma (KIT, KARS and NRAS) may be valuable molecular markers and therapeutic targets that need to be considered clinically." (PMID 36713456, 2022). "Through adjusted analysis, we delineate independent association with seminoma histology for mutations in KIT, KRAS, NRAS and Pi3K/MTOR pathway gene sets and, independent of histology, association of KIT mutation with platinum sensitivity." (PMID 32366847, 2020).
seminoma (continued). "Notably CN-Sig-6, which reflects high copy number states from focal amplification, was particularly high in seminomas with (i) increased 12p copy number, (ii) KRAS copy number and/or, (iii) KRAS mRNA expression (without KIT/KRAS/NRAS mutations)." (PMID 32366847, 2020).
endometrial carcinoma (10 papers, 2017 to 2025). A malignant tumor arising from the epithelium that lines the cavity of the uterine body. "NRAS protein is involved in many cell-cycle-regulating pathways, and nsSNPs in NRAS are associated with cancer and poor prognosis of endometrial cancer, thus serving as a novel diagnostic biomarker." (PMID 36430761, 2022). "NRAS mutation, specifically G12V, is present as a mutation hotspot in endometrial cancer." (PMID 36430761, 2022). "However, NRAS mutation generally contributes only 5% to endometrial carcinoma." (PMID 36430761, 2022). "Of note, mutations in the KRAS, NRAS, and BRAF genes have also been reported in other human malignancies, e.g., colorectal and endometrial cancers." (PMID 39456660, 2024). "Furthermore, the Kaplan–Meier bioinformatics analyses indicated that the NRAS gene deregulation affected the overall survival rate of patients with endometrial cancer, leading to prognostic significance." (PMID 36430761, 2022).
autoimmune lymphoproliferative syndrome (9 papers, 2014 to 2023). Autoimmune lymphoproliferative syndrome (ALPS) is a rare, inherited disorder characterized by non-malignant lymphoproliferation, multilineage cytopenias, and a lifelong increased risk of Hodgkin's and non-Hodgkin's lymphoma. "For example, mutations in NRAS have been associated with many cancers as well as autoimmune lymphoproliferative syndrome." (PMID 33126852, 2020). "RALD was initially classified into the type IV of autoimmune lymphoproliferative syndrome (ALPS) caused by KRAS/NRAS mutation." (PMID 31412876, 2019). "Furthermore, patients with autoimmune lymphoproliferative syndrome (ALPS) have been shown to carry somatic or germline mutations in the genes that encode FAS, Fas-ligand, caspase 10, caspase 8, NRAS, and KRAS." (PMID 32121251, 2020).
cholangiocarcinoma (9 papers, 2012 to 2025). A carcinoma that arises from the intrahepatic biliary tree (intrahepatic cholangiocarcinoma) or from the junction, or adjacent to the junction, of the right and left hepatic ducts (hilar cholangiocarcinoma). "NRAS is mutated in ~3% of cholangiocarcinomas and efforts to therapeutically target NRAS mutations in patients have been unsuccessful to date." (PMID 36056177, 2022). "Further studies are needed to define the effects of NRAS and other MAPK pathway mutations on primary and acquired resistance to ivosidenib in IDH1-mutated cholangiocarcinoma." (PMID 36056177, 2022). "Additionally, given that the in vivo spontaneous tumor model used in this study, AKT/NRAS, induces combined hepatocellular-cholangiocarcinoma, further investigation is required to assess the role of MRPL37 in cholangiocarcinoma cells." (PMID 41399509, 2025). "The NRAS G13R mutation was detected in the plasma, but not in FFPE tumor from a patient with cholangiocarcinoma." (PMID 23144797, 2012).
colorectal adenocarcinoma (9 papers, 2009 to 2026). The most common type of colorectal carcinoma. "The PBF-fixed samples of the 25 colorectal adenocarcinomas collected in the study had been routinely subjected to Sequenom MassARRAY® to screen for KRAS/NRAS/BRAF/PIK3CA mutations." (PMID 28796828, 2017). "Significant inverse correlations between DDX6 and KRAS, 4E-T and KRAS, and DDX6 and NRAS were also observed in colorectal adenocarcinoma (COAD) cell lines." (PMID 37370689, 2023). "In one study of colorectal adenocarcinoma, the frequency of different mutations (KRAS, BRAF, NRAS, and PIK3CA) were found to vary significantly with the location of the metastasis (lung, brain, and liver)." (PMID 23119210, 2012).
conjunctival melanomas (9 papers, 2017 to 2025). "BRAFV600E and NRAS mutations are present in 14–50%24–27 and 18%,28 respectively, of conjunctival melanomas." (PMID 29559732, 2018). "BRAF and NRAS mutations may be risk factorsfor recurrence and shorter survival in conjunctival melanoma, which wouldmake these patients candidates for targeted therapies and comprehensive andindividualized follow-up." (PMID 35544941, 2023). "NRAS is mutated in ~20% of conjunctival melanomas, and KIT mutations are reported in 0–7%." (PMID 32718045, 2020). "NRAS mutations have been found in almost 20% of conjunctival melanomas." (PMID 31683701, 2019). "Mutations in the CM driver genes BRAF and NRAS have been found in conjunctival melanoma." (PMID 31382694, 2019). "In patients with conjunctival melanoma, which involves dysregulation of the MAPK and PI3K/AKT/mTOR pathways, mutations in BRAF, NRAS, and NF1 are commonly observed, while KIT and PTEN mutations occur less frequently." (PMID 41001300, 2025). "Other genes involved in the development of conjunctival melanoma are TERT promoter, NRAS and NF1 in which pathogenic mutations are described." (PMID 33396957, 2020). "About 30% of BRAF- and 43% of NRAS-mutant conjunctival melanomas show gains of their oncogenic loci." (PMID 31683701, 2019).
neurocutaneous melanocytosis (9 papers, 2014 to 2025). Neurocutaneous melanocytosis (NCM) is a rare congenital neurological disorder characterized by abnormal aggregations of nevomelanocytes within the central nervous system (leptomeningeal melanocytosis) associated with large or giant congenital melanocytic nevi (CMN). "NRAS mutations are considered characteristic of primary CNS melanoma associated with neurocutaneous melanocytosis." (PMID 39273574, 2024). "One such factor that may allow for early detection is the presence of congenital melanocytic nevi, and neurocutaneous melanosis these individuals mostly have NRAS mutations, as it is frequently observed within this population." (PMID 40417324, 2025). "Furthermore, like in UMs, in two cases the SF3B1 mutation co-occurred with a GNAQ or GNA11 mutation, while in a third case (with neurocutaneous melanocytosis) an NRAS mutation was present." (PMID 26769193, 2016).
pancreatic adenocarcinoma (9 papers, 2017 to 2024). "Interestingly, components of EFR3A signaling are upregulated in human pancreatic adenocarcinoma, but not other tested RAS-mutant (KRAS, NRAS, or HRAS) cancers." (PMID 34504076, 2021).
acute leukemia (8 papers, 2015 to 2025). A clonal (malignant) hematopoietic disorder with an acute onset, affecting the bone marrow and the peripheral blood. "In the acute leukemia group, CSF3R mutations co-occurred with alterations in signaling pathway genes, including JAK3, STAT3, and NRAS." (PMID 40806796, 2025). "Of particular interest, NRAS and KRAS mutations were acquired in those patients who progressed to secondary acute leukemia or accelerated phase (MPN02, MPN04, and MPN18)." (PMID 31911629, 2020). "Co-mutations varied by subtype; MDS/MPN, NOS, and CMML cases frequently harbored mutations in epigenetic regulators (ASXL1, TET2) and splicing factors (SF3B1, SRSF2, ZRSR2), while acute leukemia cases showed alterations in JAK3, STAT3, and NRAS." (PMID 40806796, 2025).